LDHA (lactate dehydrogenase A)
Diseases named in the same sentence as LDHA in open-access papers (continued):
Sharing a sentence is not in itself a finding about the gene and the disease.
tumor (continued). "More importantly, IHC staining further verified at the clinical CRC sample scale that the density of LDHA and SCD was increased in tumor regions of obese CRC samples compared to the non-obese CRC samples." (PMID 38311726, 2024). "As potential evidence of flexibility, we also showed that tumors lacking LDHA activity exhibited increased glutamine consumption; however, we did not experimentally investigate in the previous study whether this increased glutamine metabolism enabled tumor growth in the absence of LDHA." (PMID 39303037, 2024). "We found that the mRNA expressions of LDHA (p = 0.038) and LAMP2 (p < 0.0001) were significantly higher in tumor tissues compared to the adjacent nontumor tissues." (PMID 38136340, 2023). "In addition, AGR2 may also induce the expression of lactate dehydrogenase A (LDHA), phosphoglycerate kinase 1 (PGK1), kallikrein 2 (HK2) and enolase 1α (ENO1) through the MUC1/HIF-α pathway, thus induce glycolysis of cancer cells, promote cell proliferation, migration, invasion and tumor growth." (PMID 37197416, 2023). "We used qRT-PCR to quantify the expression of LA-related genes (LDHA and LAMP2) in CRC tumor tissues and adjacent nontumor tissues (n = 64)." (PMID 38136340, 2023). "In contrast, patients in the LDHA.High or Neither groups had high and moderate LDHA levels and low CD8+ TILs, respectively, and 20-40% of patients in these clusters experienced tumor recurrence." (PMID 36505421, 2022). "We detected increased LDHA expression (p < 0.001) and reduced LDHB expression (p < 0.001) in tumor samples compared with non-tumoral adjacent tissue samples, suggesting that lactate production would be favored." (PMID 34208670, 2021). "Unlike LDHA, the expression level of LDHB varies among different tumor cell types, and its role appears more complex." (PMID 33792181, 2021). "First, elevated sLDH is not attributable to increased expression of LDHA and LDHB by tumor cells, nor does it reflect increased cellular proliferation or death." (PMID 33016647, 2020). "A negative correlation was reported in between KLF4 and LDHA expression; KLF4 under expression and LDHA overexpression were clinically correlated with disease stage and tumor differentiation in patient samples." (PMID 31146503, 2019). "The tumor size of HCC tissues from the patients undergoing hepatic resection is relatively moderate, and therefore not correlated closely with NDRG2 and LDHA expression." (PMID 31523182, 2019). "Our results showed that NDRG2 and LDHA expression correlated with histological differentiation, vascular invasion and TNM stage of HCC patients, but not correlated with tumor size of HCC patients." (PMID 31523182, 2019). "The univariate analysis results showed that NDRG2 and LDHA protein levels are closely related to overall survival of HCC patients independent of age, gender, AFP, tumor size and HBsAg." (PMID 31523182, 2019). "In the current study, PKM2 and LDHA expression scores were classified as negative or positive, which was based on the intensity and extent of PKM2 and LDHA expression across tumour areas." (PMID 26989901, 2016). "It is important to emphasize here that although tumor biology was altered by FX11 treatment, the LDHA enzyme activity was not measured in our study." (PMID 25983002, 2015). "Additionally, CCDC80's positive correlation with LDHA and negative correlation with LDHB, although weak, implies its involvement in lactate metabolism, potentially influencing the tumor microenvironment and cancer cell metabolism." (PMID 39308689, 2024). "Besides tumor suppressors, housekeeping genes, such as PUM1, B2M, ACTB, RPL13A, LDHA, and NONO, regulate basic cellular functions governing or preventing cell growth." (PMID 37109525, 2023).
tumor (continued). "However, after treating tumor cells with MG132, chloroquine, or BafA1, we found that LDHA is not degraded by the UPS." (PMID 32859246, 2020). "Notably, neither LDHA (p.adj=0.9869) nor LDHB (p.adj=0.9953) expression correlated with sLDH status, indicating that tumor cell expression of these genes did not explain differences in sLDH levels." (PMID 33016647, 2020). "To determine whether the CT inhibited the expression of STAT3, SIRT3, HIF‐1α, GLUT1, LDHA, and HK2 in vivo, we performed qRT‐PCR to detect these genes expression in tumor tissues from the mouse with or without the treatment of CT." (PMID 30094960, 2018). "Although a limited number of studies have provided evidence of mechanism between host immune suppression and the tumour glycolytic phenotype, to date, there is no concrete evidence showing a correlation between the expression of PKM2, LDHA and CD8+ effector cell infiltration." (PMID 26989901, 2016). "Interestingly, we noticed a significant inverse correlation between the PKM2 and LDHA expression and CD8+ cell infiltration, with an accumulation of CD8+ cells in tumours that did not express PKM2." (PMID 26989901, 2016). "Among genes differentially expressed between tumor samples with and without necrosis, a substantial number of hypoxia-related genes were found to be up-regulated, such as IL6, CXCL8 (IL8), SERPINE1 as well as genes involved in glycolysis (SLC2A3, LDHA)." (PMID 26485755, 2015). "Furthermore, tumor LDH activity and LDHA protein expression were not significantly correlated." (PMID 33925445, 2021).
cancer (889 papers, 2006 to 2026). A tumor composed of atypical neoplastic, often pleomorphic cells that invade other tissues. "Given that elevated LDHA levels have been observed in various types of cancer, including PDAC, and are associated with unfavorable prognosis and reduced patient survival." (PMID 40090587, 2025). "LDHA is mechanistically linked to multiple cellular processes and genetic alterations associated with cancer initiation and aggressiveness." (PMID 41368023, 2025). "The bulk of lactate production within tumors is the result of lactate dehydrogenase (LDHA/LDHB) from the two most populous tumor cell types—cancer cells and cancer-associated fibroblasts (CAFs)." (PMID 39796781, 2025). "LDHA is repeatedly associated with altered glycolytic metabolism and is considered to be a potential target for cancer treatment." (PMID 40593465, 2025). "Several genes and proteins, such as HIF‐1 and LDHA, are implicated in the glycolytic process in cancer cells." (PMID 40576161, 2025). "Recent studies have reported that LDHA is markedly highly expressed in various types of cancer and strongly associated with poor clinical prognosis and treatment outcome." (PMID 41368023, 2025). "Due to the high levels of lactate present it, LDHA (lactate dehydrogenase A) is intimately associated with the emergence of cancer." (PMID 39030594, 2024). "GSEA analysis demonstrated that several inflammation-related, energy metabolism-related, and cancer-associated pathways were hyperactivated under high LDHA expression." (PMID 38993839, 2024). "Compared to the significant carcinogenic effect of LDHA in most cancers, the association between LDHB and tumors is much more complex." (PMID 38764020, 2024). "Kaplan-Meier survival analysis showed that higher expression of LDHA was significantly associated with poor overall survival (P<0.05) and progression-free survival (P<0.001) in cancer patients." (PMID 39680520, 2024). "Up‐regulated LDHA has been associated with critical functions in cell proliferation and apoptosis in different types of cancers." (PMID 39021353, 2024). "We also presented the integrated data on mutations with important domains of LDHA in different cancer contexts, which are the higher frequency." (PMID 38709280, 2024). "Our analysis showed that in pan-cancer, LDHA mutation status was significantly correlated with OS, PFS, and DFS, but not DSS." (PMID 38709280, 2024). "The association between LDHA expression and cancer microenvironment was first evaluated by the ESTIMATE method." (PMID 39582531, 2024). "Among them, UCEC and STED had the highest mutation rate, suggesting that we should pay more attention to the connection between LDHA gene mutations and their associated cancer advancement." (PMID 38709280, 2024). "PKM2 can also function as a coactivator that stimulates hypoxia-inducible factor 1 (HIF-1) transactivation of target genes encoding PDK1, LDHA, and Glut1 in cancer cells." (PMID 38725851, 2024). "Although LDHA has shown potential in cancer therapy, its inhibition can cause a variety of off-target effects." (PMID 39678492, 2024). "By inhibiting glycolytic enzymes such as LDHA, it is possible to impede the metabolic flexibility of cancer cells, making them more susceptible to chemotherapy and reducing their ability to proliferate and metastasize." (PMID 39680520, 2024). "Some nodes had almost no orange or red bands, such as hypoxia inducible factor-1α, cancer associated fibroblasts, lactate dehydrogenase A, and epithelial mesenchymal transition, indicating that these aspects have become less studied in recent years." (PMID 38023133, 2023). "This change in the metabolic glucose pathway causes the need for overexpressed LDH enzymes in cancer tissues, turning these enzymes, and particularly LDHA isozyme, into a possible therapeutic target for the development of new anticancer therapies." (PMID 37373073, 2023).
cancer (continued). "LDHA has been implicated as a key factor in the conversion of pyruvate to lactate, resulting in the Warburg effect following PDKs activation in cancers." (PMID 37816733, 2023). "LDHA (lactate dehydrogenase A) is closely linked with cancer development because it stores high levels of lactate." (PMID 36755301, 2023). "Overexpression of LDHA has been linked to tumor initiation, maintenance and progression, as well as poor prognosis in many types of cancer, including decreased survival in GB patients treated with radiotherapy." (PMID 37298093, 2023). "LDHA, which is encoded by the c-Myc-responsive gene, is largely found in cancer and is required to maintain an increased glycolytic flux." (PMID 36984785, 2023). "As a result, LDHA is gaining popularity as a possible diagnostic or prognostic biomarker for cancer, as well as a therapeutic target for the development of future anticancer medicines." (PMID 36583135, 2023). "LDHA of the glycolysis process promotes the conversion of pyruvate to LA, which is associated with the development of various cancers, including TC." (PMID 37853445, 2023). "One such enzyme, lactic acid dehydrogenase A (LDHA), is known to be overexpressed in several cancer types and associated with poor prognosis." (PMID 35982980, 2022). "It has previously been reported that inhibiting LDHA results in a shift from glycolysis toward oxidative phosphorylation in cancer cells and that this shift is associated with a loss of an aggressive phenotype, including reduced proliferation and invasion." (PMID 35248133, 2022). "A series of research studies have suggested high activity of LDHA to be a hallmark of cancer, where the regulation of ROS plays an important role." (PMID 36407005, 2022). "The activated T cells produce more lactate via increasing lactate dehydrogenase A (LDHA) to support aerobic glycolysis, and increased LDHA is also implicated in poor prognosis of cancer patients." (PMID 35922788, 2022). "Lactate dehydrogenase A (LDHA), which converts cytosolic pyruvate into lactate, has been associated with radioresistance and chemoresistance in other cancers." (PMID 36591457, 2022). "It has been found that LDHA is strongly expressed in many human cancers and has been linked to poor patient outcomes, as seen in pancreatic, colorectal, and breast cancer, as well as RCC." (PMID 35525866, 2022). "LDH-A is considered a safe target for cancer treatment because the loss of LDH-A protein due to an inherited deletion in the LDHA gene results in only mild myopathy." (PMID 36050306, 2022). "Such as, inhibiting LDHA with FX11 (LDHA inhibitor) suppressed pyruvate to lactate conversion, and caused reductions in ATP levels and substantial oxidative stress in cancer cells." (PMID 36072431, 2022). "LDHA in solid tumors was found to be linked to aggressive cancer, which is related to its upregulation due to hypoxia." (PMID 35512017, 2022). "Expression of lactate dehydrogenase- A (LDHA), which is a key glycolytic enzyme, in cancer cells has been associated with chemotherapy and radiotherapy resistance." (PMID 34938658, 2021). "Lactate dehydrogenase A (LDHA) is overexpressed and associated with poor prognosis in many kinds of cancer." (PMID 33902615, 2021). "For example, 1-(Phenylseleno)-4-(Trifuoromethyl) Benzene (PSTMB) inhibits LDHA activity while causing cell death in a range of cancer cell lines." (PMID 34439843, 2021). "As a key enzyme evolved in glycolysis, LDHA has been reported to be up-regulated and greatly associated with poor prognosis in many kinds of cancer." (PMID 33902615, 2021). "In tumors, lactic acid dehydrogenase (LDHA) is a crucial protein for the conversion of pyruvate to lactic acid, which causes an aggressive glycolytic cancer phenotype, resulting in the Warburg effect." (PMID 34209254, 2021).
cancer (continued). "Lactate dehydrogenase A (LDH-A) is an enzyme important for controlling glycolytic metabolism, and its expression is elevated in a range of human cancer types in a manner associated with worse patient outcomes." (PMID 33072745, 2020). "LDHA overexpression has been associated with increased cancer aggressiveness and targeting has been tackled both genetically and pharmacologically." (PMID 32257942, 2020). "In summary, these observations demonstrate that the increased level, as well as efflux, of lactate in high-grade cancers are associated with increased LDHA mRNA expression, LDH activity, and MCT4 protein expression, respectively." (PMID 32110965, 2020). "The enhanced expression of lactate dehydrogenase A (LDHA) is associated with numerous cancer types and is critical for lactate efflux." (PMID 32244756, 2020). "Another enzymatic process linked to the enhanced glycolysis in cancer cells is the phosphorylation-induced activation of lactate dehydrogenase A (LDHA)." (PMID 31139559, 2019). "Up-regulation of LDHA has been found in a variety of human cancers, which is associated with cell growth, metastasis, and poor prognosis of cancer patients." (PMID 31850191, 2019). "Generating cancer cells deficient in DHA or accomplishing LDHA rescue expression has been shown to result in the attenuated metastasis of these cells in a xenograft tumor model." (PMID 31139559, 2019). "Phosphorylation significantly increased enzymatic activity of LDHA, which is associated with cancer progression." (PMID 30403008, 2018). "In keeping with our results, an increased activity of enzymes involved in glycolysis, like hexokinase and lactate dehydrogenase A (LDHA), has also been reported and linked to cancer cell." (PMID 29434411, 2017). "Elevated LDHA expression was observed in several cancers and was associated with worse overall survival." (PMID 28978061, 2017). "LDHA has been recognized as a valuable predictive/prognostic marker; its overexpression is associated with cancer invasiveness, and elevated serum lactate levels correlate with poor prognosis and resistance to chemo- and radiotherapy." (PMID 29326883, 2017). "In particular, GLUT3, HK2, PKM2 and LDHA play critical roles in initiating and maintaining the high glycolytic rates of rapidly proliferating cancer cells, and are associated with greater dependence on glycolysis than on OXPHOS." (PMID 28467784, 2017). "CSPP1 is a mitosis regulator; LGALS7 and PDE2A are overexpressed in different cancer types; LDHA encodes one of the major glycolysis enzymes." (PMID 27359056, 2016). "Taken together, these results demonstrate that the binding site of LDHA for miR-374a can generate point mutation, through which cancer cells escape from the inhibitory regulation of miR-374a." (PMID 26062441, 2015). "Elevated LDHA levels are integrally associated with many cancer types and it appears likely to be a principal factor in the altered metabolisms required for the growth and proliferation of certain tumors." (PMID 26717415, 2015). "LDHA is responsible for the conversion of pyruvate to lactate and the increased activity of this enzyme in cancer cells is strongly associated with the Warburg effect." (PMID 21541279, 2011). "An enhanced level of LDHA is observed in cancer cells and a higher level of LDHA is associated with proliferation." (PMID 19221597, 2009). "For example, research has shown that inhibiting crucial enzymes associated with lactylation, such as LDHA, can decrease lactate buildup, hinder the metabolic reprogramming of cancer cells, and consequently improve the effectiveness of chemotherapy and targeted therapies." (PMID 41458606, 2025). "We found that our lactate score could be a prognostic marker instead of LDHA for several cancer patients who possess high-frequency variants in LRGs." (PMID 38198170, 2024). "Furthermore, we also revealed an association of LDHA expression with chemotherapy drug sensitivity in pan-cancer." (PMID 38709280, 2024).